PDGFRA (platelet derived growth factor receptor alpha)
Diseases named in the same sentence as PDGFRA in open-access papers (continued):
Sharing a sentence is not in itself a finding about the gene and the disease.
tumor (continued). "Studies suggest that this gene plays a role in organ development, wound healing, and tumor progression, whereas mutant-PDGFRA is potently oncogenic." (PMID 35279104, 2022). "The Mes tumor subtype predominantly expresses fibroblastic/mesenchymal genes, such as PDGFRA, VCAM1, ZEB1, TWIST1; and extracellular matrix genes, including collagen and FN1 (bolded genes are overlapping with our negative prognostic signature)." (PMID 36555638, 2022). "Subclones harboring a PDGFRA amplicon, including one that amplified a PDGRFAY849C mutant allele, were detected in four patients; their presence in extrapontine tumor and normal brain samples imply their involvement in extrapontine invasion." (PMID 35642016, 2022). "Co-treatment significantly extended the survival of tumor-bearing mice beyond that of dasatinib treatment, providing evidence for a potential improvement in targeted therapy for PDGFRA-altered tumors." (PMID 35978801, 2022). "CAFs specifically express α-smooth muscle actin (αSMA) and platelet-derived growth factor receptor α (PDGFRα), which promote tumor metastasis and drug resistance, as well as forming a dense fibrous interstitium that encapsulates tumor tissue." (PMID 35953863, 2022). "Next, we examined the relationships between the CN gain of PDGFRA pathway and 14 tumor-related signaling pathways in the pan-cancer species." (PMID 35212838, 2022). "EGFR and PDGFRα downregulation as well as Akt-mTOR inactivation was detected in TN-treated HeLa xenograft tumor tissues." (PMID 39282148, 2022). "Genomic Sanger sequencing (left) showed two peaks representing mutant [G] and wild-type [A] nucleotides, indicating PDGFRA heterozygosity in tumor cells or contamination with the genome from healthy cells." (PMID 35075231, 2022). "Together, these results suggest that CAF-mediated induction of SLUG expression in GIST is driven by PDGFC ligand-dependent PDGFRA activation, and this correlates with tumor progression and metastasis." (PMID 33603171, 2021). "The PDGFRα + Saa3- CAFs exerted their tumor inhibition effects by overexpressing membrane palmitoylated protein 6 (Mpp6)." (PMID 33614646, 2021). "Imatinib reduces the phosphorylation of the PDGFRα/Akt axis, suppressing tumor cell growth and migration." (PMID 35087829, 2021). "There are 9 tumor core gene variations, including the KIT gene missense mutation in p.K642E (c.1924A>G) and p.T670I (c.2009C>T), KIT gene copy number gains, and PDGFRA gene copy number gains." (PMID 34449472, 2021). "Nine tumor-specific mutations were detected in ctDNA, one in KIT exon 9, six in KIT exon 11, and two in PDGFRA exon 18, all mutations were insertions or deletions, that is, indels." (PMID 34552011, 2021). "PDGFRA mutant tumor kinome profiles greatly differed from KIT/PDGFRA-WT tumors, with many kinases showing increased protein levels in PDGFRA mutant tumors relative to WT." (PMID 33320833, 2021). "Tumor cells displayed high expression of PDGFRα in 20%, and PDGF-CC in 21% of primary tumors, which correlated with the TNBC subtype." (PMID 34885027, 2021). "Knockout of HIF1A, PDGFD or PDGFRA in U251 cells inhibits cell growth and invasion in vitro and eradicates tumor growth in vivo." (PMID 34470658, 2021). "Cell 3 and its primary tumor 3 presented 28 genomic alterations in common, including gains of 4q12 (PDGFRA), an amplification of 11p15.5 (H19 and IGF2 genes), and a loss of 6p25.3 (DUSP22)." (PMID 33917394, 2021). "One of the main biological differences between adults and children is that paediatric patients lack activating mutations in the oncogenes KIT or platelet-derived growth factor receptor alpha (PDGFRA), which drive tumour formation in adults." (PMID 34769519, 2021). "PDGFRA regulates mesenchymal cell activity in the tumor microenvironment through mechanisms including vascular reorganization, proliferation, and pericyte recruitment." (PMID 34158601, 2021).
tumor (continued). "DMG tumours regularly display focal amplifications in PDGFRA and EGFR accompanied by amplifications in KIT, KDR, EGFR and MET." (PMID 34944870, 2021). "Both PDGFRα and -β are expressed by tumor cells of STS, yet expression of specifically PDGFRα is evaluated in this review as a monoclonal antibody against this receptor has been clinically tested in STS, while not against PDGFRβ." (PMID 33535618, 2021). "Inhibition of KIT and PDGFRA by tyrosine kinase inhibitors has revolutionized the treatment of GISTs and demands accurate tumor classification." (PMID 35199796, 2021). "PDGFRA aberrant activation is also correlated with several hallmarks of human cancers including tumor growth, angiogenesis, invasion, and metastasis." (PMID 33574356, 2021). "Up-regulating PDGFRα can rescue the tumor-promoting function of ldrEXOs in groups previously treated with inhibition of GRB14." (PMID 33867829, 2021). "To spatially identify putative CAFs within tumor tissue, we immunostained patient tumors with PDGFRα/β to label fibroblasts and pericytes, and ACTA2 to label activated tumor fibroblasts." (PMID 34884982, 2021). "The tumor-specific mutation was identified by sequencing the primary tumor, while the sequences for imatinib and sunitinib resistance in KIT and PDGFRA were identified from the COSMIC database." (PMID 34552011, 2021). "Reflecting the single cell data, there is an extensive PDGFRα/β population within the stroma of the tumor tissue." (PMID 34884982, 2021). "The healthy tissue had a strong percentage of ~ 90% PDGFRα+ cells that drastically decreased as the tumour grew." (PMID 34016130, 2021). "Of note, we see a striking shift from a prevalence of PDGFRα+ fibroblasts in healthy mammary fat pads, to PDGFRβ+ CAFs in tumour tissue." (PMID 34016130, 2021). "Previous studies indicated that ZBTB4 and PDGFRA played roles in tumor progression, same as our prediction." (PMID 34484284, 2021). "Increasing evidence has demonstrated that PDGFRα plays a crucial role in cancer cell proliferation, metastasis, and the tumor microenvironment." (PMID 33568640, 2021). "EGFR amplifications were more frequent in GBMs than in LGGs, while PDGFRA amplifications were more homogenous among different tumor grades." (PMID 33673104, 2021). "Whole exome sequencing of tumor specimens in this patient showed a KIT gene missense mutation in p.K642E (c.1924A>G) and p.T670I (c.2009C>T), KIT gene copy number gains, and PDGFRA gene copy number gains." (PMID 34449472, 2021). "PDGFRα + Saa3 + CAFs stimulated mice PDAC growth in both the orthotopic model and organoid cultures; however, PDGFRα + Saa3- CAFs inhibited tumor growth." (PMID 33614646, 2021). "Compared with mutational profiling routinely analyzed using tumor samples, several additional targets with currently available therapies, including IDH1, IDH2, and PDGFRA mutations, were discovered." (PMID 33816227, 2021). "These PDGFRα+ OPCs are recruited at the tumor border through PDGFC released by TME cells, including TAMs." (PMID 34690699, 2021). "On the other hand, as the tumour develops, the tumour becomes highly enriched in PDGFRβ+ CAFs, while dramatically decreasing the numbers of PDGFRα+ CAFs." (PMID 34016130, 2021). "IF revealed CXCL12 in both PDGFRα+ and PDGFRβ+ cells in tumor stroma, as well is in the adjacent matrix and blood vessels." (PMID 33753872, 2021). "With the increase of the other factors (risk score and PDGFRA and AHNAK levels), the clinical stage and the tumor stage of patients with BLCA also increased (all p < 0.01)." (PMID 34329197, 2021). "PRTPRJ exerts tumor-inhibitory effects by negatively regulating mitogenic signals originating from several oncogenic receptor tyrosine kinases, including PDGFRA." (PMID 34805171, 2021). "In vitro and in vivo studies have verified the efficacy of tyrosine kinase inhibitors, such as dasatinib, in diminishing tumour proliferation and inhibiting PDGFRA activity." (PMID 34944870, 2021).
tumor (continued). "Compared with mutational profiling routinely analyzed using tumor samples, several additional genomic alterations with currently available therapies were discovered, including IDH1, IDH2, and PDGFRA mutations." (PMID 33816227, 2021). "IHC analysis of Ki-67 expression further confirmed that these tumor tissues with attenuated PDGFRα showed decreased proliferative properties." (PMID 33568640, 2021). "Three different RTKs—epidermal growth factor receptor (EGFR), mesenchymal-to-epithelial transition (MET) and platelet-derived growth factor receptor alpha (PDGFRα)—demonstrate highly variable gene expression in individual tumor cells." (PMID 33919246, 2021). "The PDGF family can bind to the tyrosine kinase receptors, PDGFRα and PDGFRβ, and interacts with different cell types within the tumor microenvironment to enhance tumor progression and chemoresistance." (PMID 34195085, 2021). "In the case of the other three markers, FAPα, CD26 and PDGFRα, these showed divergent dynamics across time in the two tumour types." (PMID 34016130, 2021). "To determine the functional role of PDGFRα in PTEN deficiency-related cell proliferation and tumor growth, we designed additional in vitro and in vivo experiments." (PMID 33568640, 2021). "All markers showed temporal changes with a distinct switch from primarily PDGFRα+ fibroblasts in healthy mammary tissue to predominantly PDGFRβ+ CAFs in tumours." (PMID 34016130, 2021). "Plasma samples and matched tumor tissue were obtained simultaneously in cohort A from a total of 13 KIT- or PDGFRA-mutant GIST patients, and were subjected to amplicon-sequencing of 60 cancer-related genes." (PMID 32024476, 2020). "IHC staining showed that PDGFRα was not only overexpressed in non-tumor tissues among TG versus WT livers, but more dramatically increased in TG tumors than WT tumors." (PMID 32489479, 2020). "Of note, despite low levels of PDGFRα transcripts in the RNAseq data from the patient tumour, IHC confirmed high PDGFRα protein expression in the tissue." (PMID 33053751, 2020). "In this paper, we present information from image-localized biopsies that provides insight into the distribution and co-occurrence of EGFR and PDGFRA amplified sub-populations throughout GBM tumours in a cohort of patients." (PMID 33120534, 2020). "Alterations in gene copy numbers on the chromosomes where the EGFR and PDGFRA genes are found tended to occur in the early and middle phases of tumour growth, respectively." (PMID 33120534, 2020). "Unexpectedly, we found that, in addition to efficiently activate IGF1R, IGF1 also induced the phosphorylation of PDGFRα in mouse tumor OPCs." (PMID 33173731, 2020). "Sorting of tumor OPCs based on their surface expression of PDGFRα showed that PDGFRα high fraction was the subpopulation to effectively grow in vitro and generated tumors in vivo." (PMID 33173731, 2020). "In another way, the fact that PDGFRα was expressed by tumor, surrounding stromal and endothelial cells, makes this receptor a good target by specific neutralizing antibodies." (PMID 33213472, 2020). "Our study showed an association between high PDGFRα expression in ADK cells and tumor size ≤ 5 cm (P = 0.048)." (PMID 33213472, 2020). "Of genes previously reported as commonly mutated in PNETs, only PDGFRA and MTOR were found to be mutated in a few tumor samples, and other genes, including ATM, ATRX, TSC2, DAXX, VHL, and MEN1, were mutated only in individual samples." (PMID 32586046, 2020).
tumor (continued). "Together, these results indicate that early increases in CD11b + cells during tumor formation lead to increased PDGFRα + stromal cells in the tumor microenvironment." (PMID 32731354, 2020). "75% of these tumor samples showed ≥1 (likely) pathogenic mutation, including targetable mutations (e.g. EGFR, BRAF, MET, ERBB2, KIT, PDGFRA)." (PMID 32264863, 2020). "Immune contexture was examined in relation to driver gene (KIT, PDGFRA, K/P WT), tumor location (gastric and intestinal), and malignant potential (miniGIST and overt GIST)." (PMID 33048845, 2020). "Of these tumours, SDH-deficient (characterized by the loss of SDHB) and quadruple WT GIST (KIT/PDGFRA/SDH/RAS-P WT) subgroups were reported to display a marked overexpression of FGF4, identifying a putative common therapeutic target for the first time." (PMID 33199729, 2020). "Platelet derived growth factor receptor alpha (PDGFRα) has been considered as a relevant factor in tumor proliferation, angiogenesis and metastatic dissemination." (PMID 33213472, 2020). "In both of these cases we see distinct regions with EGFR and PDGFRA amplification forming in the simulated tumours of equal proportion." (PMID 33120534, 2020). "This activity leads to depletion of the stromal cells that include PDGFRα+ CD140a+ mesenchymal stem cells and α-SMA+ cancer-associated fibroblasts that ultimately results in reduction of tumor growth, invasion, and metastasis." (PMID 32765528, 2020). "Overexpression of PDGFRα in adenocarcinoma suggests its potential role in tumor cells growth and invasion." (PMID 33213472, 2020). "After obtaining single-cell suspension from explanted tumor masses, cytofluorimetric analysis of CAFs marker PDGFRα, of both, human and murine origin, was performed." (PMID 33585217, 2020). "PDGFRα showed a crucial role in therapy resistance given its impact in both stromal and tumor cells which intensify tumor proliferation." (PMID 33213472, 2020). "We first established a simple approach to enrich tumor OPCs based on the anti‐PDGFRα immunopanning technique." (PMID 33173731, 2020). "After subcutaneous inoculation of EoL-1 cells (2 × 107/100 μL) or EoL-1R cells (1 × 107/100 μL), we evaluated the tumor volume and weight and the alteration of PDGFRα activation by immunohistochemistry and Western blotting." (PMID 32903598, 2020). "(F) FACS quantification of percent PDGFRα positive cells (i.e., CAFs) per total primary tumor in size- and age-matched MMTV-PyMT (WT) or FSP1cre; Ddr2fl/fl; MMTV-PyMT (Ddr2-/- FSP1cre) tumors." (PMID 31144616, 2019). "Research models and experimental designs for further preclinical work should be selected not only on PDGFRA expression, but on the presence of activated PDGFRA as a driver of tumor growth." (PMID 31331295, 2019). "Detailed analysis of intrinsic-resistant tumours revealed several single-nucleotide variants in KRAS, NRAS, ERBB2, and PDGFRA, which likely confer resistance." (PMID 31653970, 2019). "Among 360 patients with available tumor specimens that were examined before imatinib treatment, 318 (88.3%) had KIT or PDGFRA mutation and the wild type was observed in 29 patients (8.1%)." (PMID 30693663, 2019). "High expression of PDGFRα in tumor cells, was identified as an independent indicator of poor disease-specific survival (DSS), while high expression of PDGFRα in stromal cells, was found to be a significant, but not independent, indicator of increased DSS." (PMID 31308421, 2019). "Immune cell populations analyzed include CD11b+/F4/80+ macrophages (a), CD4+ T cells (b), CD8+ T cells (c), PDGFRα fibroblasts (d), and tumor cells (e)." (PMID 30990165, 2019).
tumor (continued). "PDGFRα protein expression increased significantly in tumour-bearing mice treated with a low dose of DXR, whereas a non-significant increase was observed in mice treated with a high dose of DXR." (PMID 31370818, 2019). "GISTs WT for KIT and PDGFRA constitute a pathogenetically heterogeneous tumor group accounting for about 10–15% of GISTs." (PMID 30616628, 2019). "They found that oligodendrocyte precursor cells (OPC-like) exhibited greater self-renewal and tumor-propagating potential, and gave rise to oligodendrocyte (OC-like) and astrocytic (AC-like) populations sustained by PDGFRA signaling." (PMID 31092287, 2019). "The tumour cells showed a paranuclear dot-like staining (Golgi pattern) for PDGFRA accompanied by variable cytoplasmic and membranous staining." (PMID 30778083, 2019). "RNA interference-mediated knockdown of PDGFRA in GIST-T1 cells suppressed cell proliferation, suggesting the tumor suppressive effect of miR-34a is mediated, at least in part, through targeting PDGFRA." (PMID 29385688, 2018). "Tumour cell PDGFRα was significantly up-regulated in lymph node metastases and asynchronous recurrences." (PMID 29380207, 2018). "Activation of PDGFRA by genomic aberrations contributes to tumor progression in several tumor types." (PMID 30389923, 2018). "Activation of platelet-derived growth factor receptor alpha (PDGFRA) by genomic aberrations contributes to tumor progression in several tumor types." (PMID 30389923, 2018). "The shift was significantly skewed for PDGFRα expression in tumour cells, which was up-regulated in lymph node metastases and recurrences, and for stromal PDGFRβ expression, which was down-regulated in recurrences." (PMID 29380207, 2018). "This showed a significant association between increasing expression of both PDGFRα and PDGFRβ, and increasing PDGF-CC levels (P < 0.001 for tumour and stromal cell PDGFRα expression, P = 0.004 for stromal cell PDGFRβ expression)." (PMID 29380207, 2018). "First, overexpression of PDGFRα alone is insufficient for tumor formation, but rather requires ligand activation." (PMID 30082792, 2018). "Tumour cells displayed high expression of PDGFRα in 20%, and PDGF-CC in 21% of primary tumours, which correlated with the triple-negative subtype (TNBC)." (PMID 29380207, 2018). "Patients with high PDGF-CC had inferior prognosis (P = 0.04) in terms of 5-year DRFi, whereas PDGFRα was up-regulated in lymph node metastasis and recurrences compared to primary tumours." (PMID 29380207, 2018). "In conclusion, our results support TCs as the physiological counterpart of both IFPs and PDGFRA‐mutant GISTs, possibly pathogenetically related to both of these tumour types." (PMID 30117724, 2018). "In asynchronous recurrences, tumour cells showed high expression of PDGFRα in 23 (64%) and PDGF-CC in 8 (21%)." (PMID 29380207, 2018). "Stromal cells showed high expression of PDGFRα in 243 (50%) and PDGFRβ in 128 (27%) of the evaluated primary tumours." (PMID 29380207, 2018). "We found that high expression of PDGFRα in tumour cells of the primary tumour was correlated to subsequent first distant recurrence occurring within CNS." (PMID 29380207, 2018). "We found that Sunitinib displayed more potent anti-tumor effects in mECK36 tumors than Imatinib, which correlated with the extent of inhibition of PDGFRA phosphorylation achieved by the drugs." (PMID 29985958, 2018). "Recently, LARTRUVO (olaratumab), a PDGFRA-blocking antibody for anti-tumor activity against the PDGFRA signaling pathway, received FDA approval for STS therapy." (PMID 30598078, 2018). "Intracranial and flank implantation of these cells in immunocompromised mice led to tumor growth and an acquired VB sensitivity only in the context of PDGFRα activation, which considerably reduced tumor growth and extended survival." (PMID 30082792, 2018). "The study involved a total number of 19 tumor samples, obtained from 14 unique patients with PDGFRA D842V mutant GIST, all analyzed by WES." (PMID 29510530, 2018).